RNU6-998P (RNA, U6 small nuclear 998, pseudogene)
Gene: Small nuclear RNA gene on chromosome 4 (57,002,692 to 57,002,792, forward strand). Ensembl gene ENSG00000251703.
Homologues: Orthologues: chimpanzee U6 (99% identical), pig U6 (77% identical). Paralogues in human: RNU6-12P (83% identical), RNU6-13P (83% identical), RNU6-32P (83% identical), RNU6-1 (82% identical), RNU6-17P (82% identical), RNU6-18P (82% identical), RNU6-2 (82% identical), RNU6-33P (82% identical), RNU6-3P (82% identical), RNU6-49P (82% identical), RNU6-4P (82% identical), RNU6-5P (82% identical), and 1287 more.